RPL35 (ribosomal protein L35)
Description:
Component of the large ribosomal subunit. The ribosome is a large ribonucleoprotein complex responsible for the synthesis of proteins in the cell.
Synonyms: L35; uL29; DBA19
Tractability: Small molecule: an approved drug acts on it; a structure with a bound ligand is known; a high-quality ligand is known. PROTAC: UniProt records ubiquitination sites on it; ubiquitination databases record sites on it; its protein half-life has been measured; a small molecule that binds it is known. Other modalities: a drug acting on it is in phase 2 or 3 trials.
Target class: Other cytosolic protein
Gene: Protein-coding gene on chromosome 9 (124,857,873 to 124,862,017, reverse strand). Ensembl gene ENSG00000136942.
Subcellular location: Cytoplasm
Subcellular location (Human Protein Atlas): Cytosol; Endoplasmic reticulum
Pathways (Reactome):
Metabolism of proteins: Eukaryotic Translation Termination; Formation of a pool of free 40S subunits; GTP hydrolysis and joining of the 60S ribosomal subunit; L13a-mediated translational silencing of Ceruloplasmin expression; PELO:HBS1L and ABCE1 dissociate a ribosome on a non-stop mRNA; Peptide chain elongation; Ribosome Quality Control (RQC) complex extracts and degrades nascent peptide; SRP-dependent cotranslational protein targeting to membrane; ZNF598 and the Ribosome-associated Quality Trigger (RQT) complex dissociate a ribosome stalled on a no-go mRNA
Metabolism of RNA: Major pathway of rRNA processing in the nucleolus and cytosol; Nonsense Mediated Decay (NMD) enhanced by the Exon Junction Complex (EJC); Nonsense Mediated Decay (NMD) independent of the Exon Junction Complex (EJC)
Cellular responses to stimuli: Response of EIF2AK4 (GCN2) to amino acid deficiency
Developmental Biology: Regulation of expression of SLITs and ROBOs
Disease: Viral mRNA Translation
Metabolism: Selenocysteine synthesis
Gene Ontology:
Molecular function: RNA binding; structural constituent of ribosome; mRNA binding
Biological process: cytoplasmic translation; maturation of LSU-rRNA from tricistronic rRNA transcript (SSU-rRNA, 5.8S rRNA, LSU-rRNA); negative regulation of myoblast fusion; spermatogenesis; striated muscle contraction; translation
Cellular component: cytoplasm; cytosolic large ribosomal subunit; cytosolic ribosome; membrane; cytosol; nucleolus; large ribosomal subunit; ribosome
Genetic constraint (gnomAD): Loss-of-function variants: 2 observed, 16.1 expected, observed/expected ratio (o/e) 0.12, 90% interval 0.05 to 0.39. The synonymous counts are far from expectation, so gnomAD's model fits this gene poorly and the ratio says little. Missense variants: 111 observed, 171.06 expected, observed/expected ratio (o/e) 0.65, 90% interval 0.56 to 0.76. Synonymous variants: 93 observed, 70.71 expected, observed/expected ratio (o/e) 1.32, 90% interval 1.11 to 1.56.
Homologues: Orthologues: chimpanzee RPL35 (100% identical), macaque RPL35 (100% identical), dog RPL35 (99% identical), mouse Rpl35 (98% identical), mouse Rpl35rt (98% identical), guinea pig RPL35 (98% identical), pig RPL35 (98% identical), rat LOC120093238 (97% identical), rat AABR07031666.1 (93% identical), tropical clawed frog rpl35 (93% identical), zebrafish rpl35 (93% identical), Caenorhabditis elegans rpl-35 (67% identical), and 1 more. Paralogues in human: STT3B (38% identical), STT3A (37% identical).
Diseases named in the same sentence as RPL35 in open-access papers:
RPL35 is named in the same sentence as 21 diseases in open-access papers, as found by Europe PMC text mining. Sharing a sentence is not in itself a finding about the gene and the disease. The quoted sentences say what the papers report.
neuroblastoma (7 papers, 2019 to 2023). Neuroblastoma (NB) is the most common solid, extracranial childhood tumor. "A stable neuroblastoma cell line 5H-SY5Y in which uL29/RPL35 was knocked down showed that uL29/RPL35 depletion not only reduced cancer cell proliferation and migration but also suppressed glycolysis." (PMID 37047306, 2023). "Ectopic upregulation of uL29/RPL35 in neuroblastoma cell lines via transfection with a lentiviral vector promoted cell proliferation, migration, and invasion ability." (PMID 37047306, 2023). "uL29/RPL35 is highly expressed at both the mRNA and protein level in neuroblastoma cells, which take advantage of its numerous extraribosomal roles in mRNA translation and protein synthesis." (PMID 37047306, 2023). "uL29/RPL35 in neuroblastoma positively regulates the transcription factor HIF-1alpha to promote the Warburg effect." (PMID 37606454, 2023). "LncNB1 can bind to another protein called RPL35 in the cytoplasm, and its high expression is related with poor prognosis in neuroblastoma patients." (PMID 35592755, 2022). "The mechanism was that lncNB1 in neuroblastoma cells enhanced the synthesis of E2F1 protein by binding with ribosomal protein RPL35 and directly bonding to the gene promoter of the DEPDC1B to promote the transcription of the DEPDC18 gene." (PMID 35592755, 2022). "RPL35 promoted neuroblastoma progression via enhanced aerobic glycolysis." (PMID 37274336, 2023). "A recent study reported that lncNB1 promotes neuroblastoma tumorigenesis by interacting with RPL35." (PMID 35109823, 2022). "Importantly, lncNB1 knockdown abolishes neuroblastoma cell clonogenic capacity in vitro and leads to neuroblastoma tumor regression in mice, while high levels of lncNB1 and RPL35 in human neuroblastoma tissues predict poor patient prognosis." (PMID 31690716, 2019). "We next investigated if lncNB1, DEPDC1B, RPL35, or E2F1 is required for neuroblastoma cell proliferation and/or survival." (PMID 31690716, 2019). "Taken together, the data suggest that lncNB1, RPL35, and E2F1 regulate DEPDC1B expression in human neuroblastoma tissues, and that high levels of lncNB1, DEPDC1B, RPL35, and E2F1 expression in tumor tissues predict poor prognosis in neuroblastoma patients." (PMID 31690716, 2019). "Taken together, the data suggest that lncNB1, its binding partner RPL35 and their targets E2F1 and DEPDC1B are required for neuroblastoma cell proliferation and survival." (PMID 31690716, 2019). "In addition, in human neuroblastoma tissues, lncNB1, E2F1, or RPL35 RNA expression positively correlates with DEPDC1B RNA expression, and high levels of lncNB1, E2F1, RPL35, or DEPDC1B expression predict poorer patient outcome." (PMID 31690716, 2019). "Thus, our data demonstrate that lncNB1, its binding protein RPL35 and their target protein E2F1 and target gene DEPDC1B induce neuroblastoma cell proliferation and survival." (PMID 31690716, 2019). "As high levels of lncNB1, RPL35, E2F1, and DEPDC1B expression in tumor tissues correlate with poor prognosis in neuroblastoma patients, our findings identify lncNB1, RPL35, and DEPDC1B as important co-factors for N-Myc-driven oncogenesis and provide therapeutic targets for neuroblastoma." (PMID 31690716, 2019).
breast carcinoma (2 papers, 2012 to 2020). "The causal tumorigenic effect of overexpressed RPL15 and RPL35 was similarly demonstrated in immune-deficient NOD SCID mouse models of human breast cancer metastasis to the lung and ovary." (PMID 33120992, 2020). "This study suggests that increased protein synthesis induced by RPL15/RPL35 high expression in CTCs contributes to breast cancer progression." (PMID 33120992, 2020). "Importantly, this study also showed that in metastatic breast cancer patients expressing sex hormone receptors, characterization of CTCs with high RPL15/RPL35 expression could discriminate patients with the worse overall survival." (PMID 33120992, 2020).
colorectal cancer (2 papers, 2019 to 2022). A primary or metastatic malignant neoplasm that affects the colon or rectum. "RPL35 has recently been found to be over-expressed in human colorectal cancer tissues with unknown functions." (PMID 31690716, 2019).
COVID-19 (2 papers, 2021 to 2023). A disease caused by infection with severe acute respiratory syndrome coronavirus 2. "Through unbiased KEGG pathway analysis of DEGs between Fga−/− and WT plasma-stimulated microglia, we identified the 12 top pathways induced by fibrinogen, including ROS (for example, Hmox1, Cox7a2, Slc25a5), COVID-19 (for example, Ccl12, Rps8, Rpl35) and AD (for example, Atp5e, Psmd2, Tubb5)." (PMID 37291385, 2023).
Diamond-Blackfan anaemia (2 papers, 2022 to 2023). "At present, studies on the identified diseases related to RPL35 mainly focus on Diamond-Blackfan anaemia (DBA)." (PMID 35109823, 2022). "The importance of critical interfaces between domains I, II and the 5.8S rRNA is further highlighted by the finding that key stabilizers of these sites include Rpl17 (RPL17 in humans) and Diamond-Blackfan anemia proteins Rpl26 (RPL26) and Rpl35 (RPL35) 24,25." (PMID 37037974, 2023).
viral infection (2 papers, 2022 to 2025). "The results demonstrated that VP2 interacts with endogenous RPL35 under viral infection conditions." (PMID 41065387, 2025). "Additionally, experiments on endogenous ubiquitination demonstrated that RPL35 promoted both total ubiquitination and K48-linked ubiquitination of endogenous VP2 during viral infection." (PMID 41065387, 2025).
Alzheimer disease (1 paper, 2024). A progressive, neurodegenerative disease characterized by loss of function and death of nerve cells in several areas of the brain leading to loss of cognitive function such as memory and language. "The down-regulated DEGs in NM versus NN were primarily focused on ribosome (about 26 DEGs, including RPL37A and RPL35), Alzheimer’s disease (about 20 DEGs, including SNCA and COX8A), and retrograde endocannabinoid signaling (about 6 DEGs, such as NDUFA1 and GNG5)." (PMID 38660519, 2024).
breast tumor (1 paper, 2024). "RPL15 (eL15) and RPL35 (uL29) expression in circulating breast tumor cells is correlated with increased proliferation and reduced apoptosis, as well as higher metastatic capacity." (PMID 38729158, 2024).
cervical carcinoma (1 paper, 2022). A carcinoma arising from either the exocervical squamous epithelium or the endocervical glandular epithelium. "In addition, one study speculated that the expression of RPL35 could predict lymph node metastasis in patients with early-stage cervical carcinoma." (PMID 35109823, 2022).
melanoma (1 paper, 2025). A malignant, usually aggressive tumor composed of atypical, neoplastic melanocytes. "SHAP value analysis ranked RPL35, KHDRBS3, ATP6V0D1, and CRIP2 as the most important contributors to melanoma classification." (PMID 40909289, 2025).
osteoarthritis (1 paper, 2025). A noninflammatory degenerative joint disease occurring chiefly in older persons, characterized by degeneration of the articular cartilage, hypertrophy of bone at the margins and changes in the synovial membrane. "Although RPL35’s association with osteoarthritis and other skeletal disorders indicates broader musculoskeletal implications, our focused proteomic profiling reveals that RPs in AS hip tissues predominantly interact through pathways distinct from canonical translation." (PMID 40438364, 2025).
infection (9 papers, 2014 to 2025). The state of being infected such as from the introduction of a foreign agent such as serum, vaccine, antigenic substance or organism. "At 8 and 12 h post-infection (hpi), RPL35-expressing cells exhibited reduced intracellular viral RNA levels compared to control cells, along with significantly decreased extracellular viral RNA levels." (PMID 41065387, 2025). "Infection from HIV-1 (SERINC5+) in macrophages upregulated RPL35 by ~5-fold and DRAP1 by ~3-fold at the RNA level, which was, importantly, reversed when the viruses were produced in the presence of viral accessary protein Nef." (PMID 36976020, 2023). "The aberrant localization of RPL35 induced by infection may selectively affect the translation of viral and host mRNAs; however, the mechanism underlying this selective effect requires further in-depth investigation." (PMID 41065387, 2025). "Infection from HIV-1 (SERINC5+) upregulates RPL35 and DRAP1 in macrophages." (PMID 36976020, 2023). "The suppression of viral RNA synthesis mediated by RPL35 may result from infection-induced impairment of its nucleocytoplasmic trafficking, which disrupts the production of host proteins necessary for viral RNA replication, thereby indirectly attenuating viral RNA synthesis." (PMID 41065387, 2025). "We have also shown that Tat binding to MCE1 is lost only in the case when the infection is initiated with SERINC5 incorporated virus and upon upregulation of RPL35 and DRAP1." (PMID 36976020, 2023). "Since RPL35 and DRAP1 interact with MCE1 exclusively during HIV-1 (SERINC5+) infection, we evaluated whether the expression levels of these host genes affected the viral RNA capping and found that overexpression of the host genes reduced the viral RNA capping even for HIV-1 (SERINC5−)." (PMID 36976020, 2023).
RPL35 also shares sentences with these, for which no sentence is quoted: cancer (6 papers); tumor (4); B-cell lymphoma (1); depression (1); Diamond-Blackfan anemia (1); lymph node metastasis (1); macrosomia (1); pancreatic cancers (1); psoriasis (1).